MIR345 (microRNA 345)
Synonyms: hsa-mir-345; MIRN345; mir-345
Gene: MicroRNA gene on chromosome 14 (100,307,859 to 100,307,956, forward strand). Ensembl gene ENSG00000198984.
Gene Ontology:
Biological process: miRNA-mediated post-transcriptional gene silencing
Cellular component: RISC complex
Homologues: Orthologues: chimpanzee ptr-mir-345 (100% identical), pig ssc-mir-345-1 (82% identical), guinea pig MIR345 (81% identical), mouse Mir345 (78% identical), rat Mir345 (78% identical), dog MIR345 (58% identical).